S100A8 (S100 calcium binding protein A8)
Diseases named in the same sentence as S100A8 in open-access papers (continued):
Sharing a sentence is not in itself a finding about the gene and the disease.
breast carcinoma (continued). "To further explore the clinical significance of S100A8/A9 and DACH1 levels in breast cancer, we performed a combined analysis using the IHC staining scores of S100A8, S100A9, and DACH1." (PMID 38093319, 2023). "The results of pooled analysis showed that both S100A8 and S100A9 mRNA abundances were dramatically upregulated in grade 3 breast cancer tissues in comparison with grade 1–2 cancer tissues." (PMID 38093319, 2023). "For instance, breast cancer cells overexpress CXCL1/2 to attract myeloid cells into tumors, which in turn generate S100A8/A9 to confer chemoresistance properties to cancer cells and support their survival." (PMID 38093319, 2023). "We previously revealed an unusual role of ZEB1 in the S100A8/A9-mediated metastasis in breast cancer cells that expressed ZEB1 at a significant level and showed that the ZEB1 was activated on the MCAM-downstream pathway upon S100A8/A9 binding." (PMID 36910659, 2023). "Similar to S100A8, S100A9 expression was significantly upregulated in ER- (P < 0.0001), PR- (P < 0.0001), Her2+ (P = 0.00097) breast cancer." (PMID 38093319, 2023). "TNM plot analyzer, Kaplan-Meier plotter, Meta-analysis, GEPIA2 and GOBO publicly available datasets were used to evaluate the clinical significance of S100A8/A9 and expression levels of S100A8/A9, RAGE and Filamin family members in breast cancer (BC) subtypes." (PMID 35655319, 2022). "S100A8 and S100A9 had significantly higher expression levels with p-values of 0.0069 and 0.0048 in breast cancer patients, respectively, with an increased fold-change of 7.8 and 10.2 compared to controls." (PMID 35471994, 2022). "In colon cancer, S100A8 and S100A9 induce RAGE- and carboxylated glycan-dependent phosphorylation of ERK1/2 and SAPK/JNK, but in prostate and breast cancer, they promote p38 phosphorylation." (PMID 36613714, 2022). "Elevated levels of S100A8 and S100A9 detected in tear samples from breast cancer patients supports previously reported results indicating elevated levels in serum and tissue of breast cancer patients." (PMID 35471994, 2022). "Previous research groups have reported that S100A8 and S100A9 were elevated in serum and tissue of breast cancer patients." (PMID 36284356, 2022). "Similar to the observed LC-MS/MS results, S100A8 (p-value <0.0001) and S100A9 (p-value <0.0001) showed significantly higher expression in breast cancer patients." (PMID 35471994, 2022). "S100A8 and S100A9 specifically have been shown to have altered expression levels in breast cancer tissues compared with normal tissues, with increased expression levels associated with non-functional BRCA1 (BReast CAncer gene 1)." (PMID 35471994, 2022). "Differently, S100A7, S100A8 and S100A9 are co-amplified on chromosome 1q21.3 in breast cancer, have similar functions and cooperate with each other to induce target protein phosphorylation leading to tumor recurrence and chemoresistance." (PMID 35463335, 2022). "We also examined the S100A8 and S100A9 mRNA levels in normal breast and breast cancer tissues using RNA sequencing data comprised of 65 normal and 68 cancer tissues." (PMID 33446797, 2021). "After analyzing TCGA-BRCA and breast cancer metastatic cohort (GSE110590) gene expression data, we found that S100A8 transcripts are altered in metastatic sites with a higher expression tendency in metastasis." (PMID 34072157, 2021). "To further assess the prognostic relevance of elevated levels of S100A8 and S100A9 in breast cancer, we utilized a publicly available cohort of combined clinical microarray data containing response rates to various therapies." (PMID 34771752, 2021). "In contrast, S100A7, S100A8 and S100A9, all of which are co-amplified on chromosome 1q21.3 in breast cancer, have similar functions and work together to induce target protein phosphorylation." (PMID 32929353, 2020).
breast carcinoma (continued). "S100a8 is elevated in ER- and HER2+ subtypes of breast cancer and contributes towards cancer cell survival and metastasis, thereby contributing to delayed progression of PyMT/p11-KO tumors." (PMID 33297495, 2020). "For example, high mRNA levels of S100A8 and S100A9 predict worse prognosis in the luminal A-type breast cancer, while increased levels of S100A10, S100P, and S100Z showed shorter OS in patients with the basal-like subtype." (PMID 32722137, 2020). "Another study demonstrated that breast cancer cells secreted MIF and led to the recruitment of S100A8+ myeloid cells, thereby promoted tumorigenesis." (PMID 31036057, 2019). "The aim of this study was to evaluate the simultaneous serum-based level of S100A8/A9 and CA15-3 as well-illustrated cancer biomarkers, as well as their prognostic value in breast cancer patients and healthy matched controls." (PMID 31528166, 2019). "In a mouse breast cancer lung metastasis animal model, CCL2 also promotes MDSC migration and triggers S100A8/A9 secretion." (PMID 30792719, 2019). "The results showed that tumor grade (OS: p = 0.021; DFS: p = 0.030) and S100A8 expression (OS: p = 0.003; DFS: p = 0.002) were significant prognostic factors for breast cancer patients." (PMID 30456203, 2018). "Therefore, the detection of S100A8 expression by IHC might have prognostic value in breast cancer." (PMID 30456203, 2018). "The results showed that the expression of S100A8 at the mRNA level in TNBC and ER-negative breast cancer patients was higher than that in luminal subtype breast cancer patients." (PMID 30456203, 2018). "S100A8 and S100A9 usually form a heterodimer called calprotectin, which is expressed in immune cells infiltrating the breast cancer stroma." (PMID 30456203, 2018). "Infiltrating S100A8+ myeloid cells coordinated by macrophage inhibitory factor (MIF) result in poor overall survival (OS) and shorter metastasis-free survival in breast cancer patients." (PMID 30456203, 2018). "S100A8/A9 at 10 μg/ml induces significant growth-promoting activity in MCF-7, MDA-MB231, and SHEP breast cancer cell lines, whereas the S100A8/A9 protein at higher concentrations does not enhance cellular proliferation." (PMID 29942307, 2018). "Our findings supported by human data show that breast cancer patients with high-levels of IL-1β, CXCL1, CCL2, S100A8, VEGF, and IL-8 would show worse clinical outcomes." (PMID 29262555, 2017). "S100A5, S100A6, S100A8 and S100A9 were correlated with prognosis in luminal A type breast cancer patients." (PMID 28051137, 2017). "Metastatic breast cancer is known to secrete CCL2 39, which can stimulate MDSC-like and trigger S100A8/A9 release." (PMID 28744322, 2017). "We evaluated the association between the expression of IL-1β plus CXCL1 plus CCL2 plus S100A8 plus VEGF plus IL8 and outcomes in several cohorts of breast cancer patients." (PMID 29262555, 2017). "Furthermore, recent studies suggest that S100A8 and S100A9 function as transcriptional coactivators in the regulation of gene expression during the transformation of breast cancer cells." (PMID 41009692, 2025). "Furthermore, S100A8 and S100A9 gene expression showed an ER-negative status in breast cancer patients." (PMID 39594999, 2024). "The amplification of S100A8 did not seem connected with the expression of the S100A8 protein in breast cancer." (PMID 39594999, 2024). "S100A8/A9 was found to show significant pro-growth activity against certain breast cancer cell lines at low protein levels, while high concentrations of the S100A8/A9 protein did not promote cell proliferation." (PMID 39329929, 2024). "Furthermore, we devised a comprehensive prognostic model that combines S100A8/A9 with DACH1, a widely recognized tumor suppressor in breast cancer, to distinguish breast cancer patients with unfavorable prognoses." (PMID 38093319, 2023). "The combination of S100A8/A9 and DACH1 could more effectively differentiate breast cancer patients with poor outcomes." (PMID 38093319, 2023).
breast carcinoma (continued). "Additionally, the IHC staining also demonstrated that S100A8 and S100A9 were negatively correlated with DACH1 expression in breast cancer samples." (PMID 38093319, 2023). "Moreover, intracellular S100A8 can suppress invasion and epithelial–mesenchymal transition (EMT) in breast cancer cells." (PMID 37701037, 2023). "Here, we analyzed the correlation among S100A8, S100A9, and DACH1 mRNA expression in breast cancer." (PMID 38093319, 2023). "The serum S100A8 level was notably higher in Grade 3, ER-negative, PR-negative, Her2-positive, basal-like, and Her2-overexpressed breast cancer patients." (PMID 38093319, 2023). "Although we’ve demonstrated the up-regulation of S100A8/A9 expression in mouse fat pad xenograft tumors, we were not able to examine the S100A8/A9 up-regulation in human breast cancer tissues in the present study." (PMID 33446797, 2021). "Since S100A8/A9 is not released by the tumor cells themselves, at least not in the case of murine 4T1 breast cancer, there is a number of implications." (PMID 33401528, 2021). "Furthermore, in a breast cancer mouse model, it was proven that MDSC not only express the receptor for S100A8/9 but also express these proteins themselves." (PMID 34065891, 2021). "S100A8 and S100A9 showed distinct up-regulation in the co-cultured MCF10A cells and their microenvironmental upregulation was also observed in the orthotropic xenograft of syngeneic mouse mammary tumors." (PMID 33446797, 2021). "Our results have shown that the serum level of S100A8/9 was significantly higher in patients vis-a-vis healthy controls, and this over-expression was positively correlated with tumor size, which is in line with the reported higher gene expression of S100A8 and S100A9 in breast cancer." (PMID 31528166, 2019). "It was demonstrated that the percentage of S100A8-positive cells in recurrent breast cancer patients was significantly higher than that in breast cancer patients without recurrence." (PMID 30456203, 2018). "IHC analysis was performed to detect the expression levels of S100A8 in para-carcinoma and breast cancer tissue from patients without and with relapse." (PMID 30456203, 2018). "Thus, down-regulation of S100A8 and S100A9 genes by 4-OH-TAM can be related to the inhibition of the invasive and migratory phenotypes of human breast cancer cells, particularly in ER--breast cancer cells." (PMID 29416786, 2018). "The average expression of S100A8 in metastatic breast cancer patients was also higher than that in breast cancer patients without metastasis." (PMID 30456203, 2018). "The expression of S100A8 at the protein level was correlated with tumor stage (p < 0.001), ER status (p < 0.001), PR status (p < 0.001), HER2 status (p = 0.012), and relapse (p = 0.002) in breast cancer patients." (PMID 30456203, 2018). "In addition, S100A8 and S100A9 enhance chemoresistance of breast cancer cells by activating the pro-survival ERK1, ERK2 and ribosomal protein S6 kinase β1 pathways." (PMID 28051137, 2017). "Not unexpectedly, our results confirmed that S100A8 and S100A9 were significantly associated with lower OS for all breast cancer, especially in luminal A type, lymph node negative and grade 2 breast cancer patients." (PMID 28051137, 2017). "Recent experimental studies showed that exogenously added S100A8 and S100A9 proteins enhanced the proliferation of tumor cells such as breast cancer cells, colorectal and pancreatic cancer cells; the overexpression of intracellular S100A8 protein had a growth-promoting activity in keratinocytes." (PMID 28637501, 2017). "Similarly, the binding of S100A8/A9 to RAGE was shown to promote migration and invasion of human breast cancer cells through actin polymerization and epithelial–mesenchymal transition." (PMID 25872475, 2015). "Moreover, S100A8 and S100A9 seem to suppress breast cancer by activating mesenchymal to epithelial transition." (PMID 25298751, 2014).
breast carcinoma (continued). "HV-68 infected mice with metastatic breast cancer disease had no increases in S100A8/A9 levels and no significant increases in the numbers or activation of CD11b+Gr-1+MDSCs when compared to mock treated mice with breast cancer." (PMID 22946998, 2012). "Furthermore, miR-185-5p inhibited the S100A8/A9 induced EMT of breast cancer cells by the NF-kB/Snail signaling pathway and was negatively associated with RAGE." (PMID 39830522, 2024). "In addition, evaluation of S100A8 and S100A9 has been limited to only breast cancer." (PMID 36284356, 2022). "To further elucidate the specific cell–cell communication by S100A8/S100A9 signaling in the tumor ecosystem, we analyzed RAGE and TLR4 signaling via measuring ligand and receptor expression in different cell types using single-cell RNA-seq data from two breast cancer metastases." (PMID 35440136, 2022). "Concentrations of S100A8 and S100A9 were found to be elevated in breast cancer (mean concentration of 2997.17 pg/ml for S100A8 and 5729.19 pg/ml for S100A9) compared with the control group (mean concentration of 1003.92 pg/ml for S100A8 and 2107.35 pg/ml S100A9)." (PMID 35471994, 2022). "Three biomarkers, S100A8 (p-value = 0.0069, 7.8-fold increase), S100A9 (p-value = 0.0048, 10.2-fold increase), and Galectin-3 binding protein (p-value = 0.01, 3.0-fold increase) with an increased expression in breast cancer patients were selected for validation using ELISA." (PMID 35471994, 2022). "Furthermore, S100A8-overexpressing MCF10A cells showed increased cell migration, invasion, colony formation, and 3-dimensional cell growth which are characteristics of the MCF10A cells directly co-cultured with breast cancer cells." (PMID 33446797, 2021). "Previous studies suggested that UBE2C expression was accompanied by that of other biomarkers such as AZGP-1, prolactin-inducible protein, and S100A8 or with pituitary tumor-transforming 1 (PTTG1), Survivin and thymidin kinase 1, which might improve outcome prediction in breast cancer." (PMID 24699941, 2014). "Furthermore, a significant (p < 0.05) positive correlation between ESR1 and S100A8 and S100A9 gene expression levels was observed in basal breast cancer patients; whereas such a correlation was significantly (p < 0.05) negative in the Her2, Luminal A, and Luminal B types of breast cancer patients." (PMID 39594999, 2024).
rheumatoid arthritis (85 papers, 2006 to 2025). A chronic, systemic autoimmune disorder characterized by inflammation in the synovial membranes and articular surfaces. "Beyond acting as antibacterial cytokines, S100A8/A9 is also associated with metabolic and autoimmune diseases such as obesity, diabetes, and rheumatoid arthritis." (PMID 38093319, 2023). "The serum S100A8/A9 complex has been shown to be associated with disease activity in inflammatory diseases such as rheumatoid arthritis, adult-onset Still’s disease, Sjögren’s syndrome, ankylosing spondylitis, Crohn’s disease, and ulcerative colitis." (PMID 37165399, 2023). "In extracellular fluid, increased levels of S100A9/S100A8 etherodimer were reported in numerous inflammation-associated conditions, such as rheumatoid arthritis, Crohn’s Disease, colorectal cancer and in GCF (Gingival Crevicular Fluid) of patients suffering from gingivitis and periodontitis." (PMID 26719749, 2015). "The S100A8/A9 complex inhibits the activity of matrix metalloproteinases and has been used as a marker for rheumatoid arthritis, colorectal cancer, inflammatory bowel disease, and periodontitis." (PMID 39620241, 2025). "As an inflammatory cytokine, S100A8/A9 has been used as a valid marker for predicting the severity of various inflammatory diseases, such as inflammatory bowel disease and rheumatoid arthritis." (PMID 37180431, 2023). "The interaction of monocytes with inflamed endothelium results in the release of S100a8/a9 in juvenile rheumatoid arthritis." (PMID 37396347, 2023). "S100A8/ S100A9 is the most abundant protein in rheumatoid arthritis synovial fluid (SF) and has a key role in promoting IL-6 expression in fibroblast-like synoviocytes (FLS)." (PMID 36700196, 2022). "The importance of S100A8/A9 as a biomarker for inflammatory diseases such as rheumatoid arthritis as well as its multiple extracellular functions have been described in detail over the past years." (PMID 34445548, 2021). "In the periphery, S100A8 is involved in pathological cascades in multiple diseases such as rheumatoid arthritis, systemic erythematosus lupus, and cancer." (PMID 34449045, 2021). "Recent studies have identified dysregulated miR-146a-5p and miR-155-5p miRNAs as drivers of phosphorylated S100a8/a9 heterodimers and the production of proinflammatory cytokines in female rheumatoid arthritis patients." (PMID 34220829, 2021). "High levels of S100A8/9 have been found in Alzheimer’s disease, rheumatoid arthritis, Crohn’s disease, cystic fibrosis, and several cancers, such as colorectal carcinoma, prostate cancer, and gastric cancer." (PMID 34199060, 2021). "It has been demonstrated that S100A8 levels are increased locally in sites of inflammation as well as in the general circulation in rheumatoid arthritis patients." (PMID 32272779, 2020). "The fluctuation of serum S100A8/A9 is observed in various inflammatory diseases, such as rheumatoid arthritis, skin disease and so on." (PMID 32140589, 2020). "S100A8/A9 (calprotectin) has been reportedly recognized as a sensitive biomarker for inflammatory diseases, such as rheumatoid arthritis, psoriasis, and vasculitis." (PMID 32140589, 2020). "The S100A8/A9 complex also has been shown to participate in multiple diseases such as asthma and rheumatoid arthritis." (PMID 32448169, 2020). "S100A8-producing macrophages were significantly elevated in rheumatoid arthritis patients treated with high-dose steroids." (PMID 32425933, 2020). "Elevated S100A8 and S100A9 protein levels are a hallmark of numerous pathological conditions associated with inflammation (e.g. rheumatoid arthritis, systemic lupus erythematosus, giant cell arteritis, cystic fibrosis, and inflammatory bowel diseases)." (PMID 30870488, 2019). "There have been several reports about the pivotal role of S100A8/A9 as a biomarker in inflammatory diseases like rheumatoid arthritis, acute myocardial infarction, or chronical inflammatory bowel diseases." (PMID 29180834, 2017).